DDHD2 (DDHD domain containing 2)
Description:
Diacylglycerol (DAG) and triacylglycerol (TAG) lipase required for proper lipid homeostasis in the central nervous system. It cooperates with PNPLA2/ATGL in neuronal TAG catabolism and hydrolyzes sn-1,3 DAG downstream of PNPLA2/ATGL (By similarity). In vitro, it also acts as a phospholipase that hydrolyzes preferentially phosphatidic acids, including 1,2-dioleoyl-sn-phosphatidic acid, phosphatidylcholine and phosphatidylethanolamine. Specifically binds to phosphatidylinositol 3-phosphate (PI(3)P), phosphatidylinositol 4-phosphate (PI(4)P), phosphatidylinositol 5-phosphate (PI(5)P) and possibly phosphatidylinositol 4,5-bisphosphate (PI(4,5)P2). May be involved in the maintenance of the endoplasmic reticulum and/or Golgi structures. May regulate the transport between Golgi apparatus and plasma membrane.
Synonyms: KIAA0725; SAMWD1; SPG54; p125B; iPLA1gamma; iPLA1γ; iPLA(1)gamma; iPLA1A
Tractability: PROTAC: ubiquitination databases record sites on it; its protein half-life has been measured.
Target class: Enzyme; Hydrolase
Gene: Protein-coding gene on chromosome 8 (38,225,218 to 38,275,558, forward strand). Ensembl gene ENSG00000085788.
Subcellular location: Cytoplasm, cytosol; Endoplasmic reticulum-Golgi intermediate compartment; Golgi apparatus, cis-Golgi network
Subcellular location (Human Protein Atlas): Cytosol; Centriolar satellite
Pathways (Reactome):
Metabolism: Synthesis of PA
Gene Ontology:
Molecular function: triacylglycerol lipase activity; diacylglycerol lipase activity; phospholipase activity; metal ion binding; monoacylglycerol lipase activity; phospholipase A1 activity
Cellular component: cytosol; COPII-coated ER to Golgi transport vesicle; endoplasmic reticulum-Golgi intermediate compartment; Golgi apparatus; membrane
Genetic constraint (gnomAD): Loss-of-function variants: 36 observed, 62.71 expected, observed/expected ratio (o/e) 0.57, 90% interval 0.44 to 0.76. The upper end of that interval is the gene's LOEUF score, 0.76, which puts it in group 3 of 6, group 1 being the genes least tolerant of losing a copy. Missense variants: 542 observed, 664.84 expected, observed/expected ratio (o/e) 0.82, 90% interval 0.76 to 0.88. Synonymous variants: 211 observed, 236.43 expected, observed/expected ratio (o/e) 0.89, 90% interval 0.8 to 1.
Homologues: Orthologues: chimpanzee DDHD2 (99% identical), macaque DDHD2 (98% identical), dog DDHD2 (95% identical), rabbit DDHD2 (93% identical), pig DDHD2 (93% identical), rat Ddhd2 (89% identical), mouse Ddhd2 (89% identical), guinea pig DDHD2 (83% identical), tropical clawed frog ddhd2 (63% identical), zebrafish ddhd2 (53% identical), Drosophila melanogaster PAPLA1 (31% identical). Paralogues in human: SEC23IP (55% identical), DDHD1 (25% identical).
Diseases named in the same sentence as DDHD2 in open-access papers:
DDHD2 is named in the same sentence as 72 diseases in open-access papers, as found by Europe PMC text mining. Sharing a sentence is not in itself a finding about the gene and the disease. The quoted sentences say what the papers report.
hereditary spastic paraplegia (16 papers, 2015 to 2025). Hereditary spastic paraplegias (HSP) comprise a genetically and clinically heterogeneous group of neurodegenerative disorders characterized by progressive spasticity and hyperreflexia of the lower limbs. "Patients with DDHD2 mutations had lipid accumulation in the brain and hereditary spastic paraplegia." (PMID 39062593, 2024). "Patients with loss-of-function mutations in the human DDHD2 gene suffer from a complex hereditary spastic paraplegia (SPG54) that includes lower limb weakness, gait impairment, and intellectual disability." (PMID 37832604, 2023). "In the case of LD lipolysis, recessive mutations in a brain TAG lipase (DDHD Domain-Containing 2 (DDHD2)), which hydrolyzes LD core lipids, underlie a form of complex hereditary spastic paraplegia." (PMID 35493070, 2022). "Mutation of the DDHD2 gene causes hereditary spastic paraplegia (SPG54), an inherited neurological disorder characterized by lower limb spasticity and weakness." (PMID 30038238, 2018). "Although neurons normally do not contain large amounts of TGs or LDs, deficiency of the neuronal TG lipase DDHD2/Spg54, which is also associated with development of hereditary spastic paraplegia, causes TG accumulation in neurons, providing evidence that these cells can synthesize and degrade TGs." (PMID 37443287, 2023). "Mutations in the phospholipase A1 family members DDHD1 and DDHD2 have recently been linked to autosomal-recessive forms of hereditary spastic paraplegia (HSP)." (PMID 25691889, 2015). "Here we show that acute block of a neuron-specific triglyceride lipase, DDHD2 (a genetic driver of complex hereditary spastic paraplegia), or of the mitochondrial lipid transporter CPT1 leads to rapid onset of torpor in adult male mice." (PMID 40595405, 2025). "To investigate the function of DDHD2 in mediating synaptic plasticity and memory formation, we used a DDHD2 knockout mouse model of hereditary spastic paraplegia (HSP)." (PMID 38316990, 2024). "However, further studies using DDHD2-KO mice and cells transfected with DDHD2 bearing inactivating mutations found in a complex form of hereditary spastic paraplegia (HSP) unambiguously revealed that DDHD2 behaves in vivo as a TAG lipase." (PMID 39125098, 2024). "Neurons initiate lipolysis independently of ATGL via DDHD domain-containing 2 (DDHD2), a multifunctional lipid hydrolase whose dysfunction causes neuronal TAG deposition and hereditary spastic paraplegia." (PMID 37832604, 2023). "DDHD2 KO mice also show significant functional deficits, consistent with CNS impairment (intellectual disability and ataxia) that presents in hereditary spastic paraplegia-54 patients." (PMID 38183680, 2024).
Spastic paraplegia (12 papers, 2014 to 2025). Complete loss of the ability to move the lower limbs accompanied by spasticity of the lower limbs. "DDHD2 knock-out mice display learning and memory symptoms recapitulating the cognitive and neuromuscular deficits displayed in human spastic paraplegia (HSP) patients with DDHD2 variants." (PMID 40528004, 2025). "DDHD2 Gene (NM_015214.3): A homozygous missense variant (c.2065G > T; p.Asp689Tyr) responsible for spastic paraplegia 54, autosomal recessive (OMIM 615033)." (PMID 39281811, 2024). "In family 9, a single affected individual was found to have a homozygous missense variant (c.2065G > T; p.Asp689Tyr) in the DDHD2 gene (NM_015214.3), which is responsible for Spastic paraplegia 54, autosomal recessive (OMIM 615033)." (PMID 39281811, 2024). "DDHD2 knockout is a model for human spastic paraplegia (HSP), a disorder characterised by progressive intellectual disability and neuromuscular deficits." (PMID 38316990, 2024). "In further support of a neuron-specific TG lipase, the human hereditary spastic paraplegia gene DDHD2, a member of the iPLA1/PAPLA1 family, was proposed to be the main lipase regulating TG metabolism in the mammalian brain." (PMID 34788284, 2021). "DDHD2 mutations cause SPG54, which is associated with very early-onset spastic paraplegia (before 2 years of age), intellectual disability, a thin corpus callosum (TCC) and optic nerve involvement." (PMID 27679996, 2016). "However our findings on the role of a wild type DDHD domain in preventing retinal degeneration provide an insight into the cellular mechanisms that could explain the neurodegenerative phenotype seen in spastic paraplegias, in patients carrying mutations in human DDHD1 and DDHD2." (PMID 33597200, 2021). "DDHD2 is mutated in SGP54, which is usually characterized by very early onset spastic paraplegia, intellectual disability, and white matter abnormalities, but adult onset forms have been reported for both DDHD1 and DDHD2." (PMID 32180696, 2020).
Intellectual disability (9 papers, 2014 to 2024). "Mutations of DDHD2 have been linked to the genetic disorder known as complex hereditary spastic paraplegia (CHSP), leading to tonic spasms of the lower limbs and intellectual disability." (PMID 35782380, 2022). "Using whole exome sequencing, we identified a homozygous missense mutation in DDHD2, whose mutations were recently identified as the cause of early-onset ARHSP with intellectual disability." (PMID 25417924, 2014). "Alteration in the phospholipase gene SPG54/DDHD2 at p11.23 induces the HSP phenotype at early ages, with intellectual disability and white matter abnormalities observed in scans." (PMID 35163618, 2022).
breast carcinoma (7 papers, 2010 to 2022). "Further bioinformatics analysis implicated miR-503 and DDHD2 in breast cancer tumorigenesis." (PMID 25653011, 2015). "Our analysis further linked miR-503 to ER+ breast cancer through DDHD2." (PMID 25653011, 2015). "DDHD2 was recently widely discovered as an oncogene in breast cancer that stimulates the growth of cancer cells, and DDHD2 was verified for the first time to act as a tumor driver gene in PTC progression." (PMID 33479208, 2021). "DDHD2 was previously shown to promote tumorigenesis in breast cancer by cooperating functionally with Myc to enhance breast cancer cell growth." (PMID 25653011, 2015). "DDHD2 has previously been shown to be tumor promoting in breast cancer by cooperating functionally with Myc to stimulate breast cancer cell growth." (PMID 25653011, 2015). "Additional bioinformatic analysis revealed a link between miR-503, DDHD2, and breast cancer." (PMID 25653011, 2015). "Moderate repression of multiple key regulatory genes can have large phenotypic effects in concert, and miR-503 may conceivably inhibit breast cancer tumorigenesis by repressing multiple previously known targets in addition to DDHD2." (PMID 25653011, 2015). "Among the altered genes, ARHGAP26 and MLLT1 have been associated with leukemia-specific translocations, DDHD2, FGFR1 and PTPN1 have tumor-promoting potential in breast cancer, and CTNNA3 may promote tumor formation in urothelial cancer." (PMID 20428235, 2010). "Our results provide an extensive genome wide set of targets for miR-503, miR-103, and miR-494, and suggest that miR-503 may act as a tumor suppressor in breast cancer by its direct non-canonical targeting of DDHD2." (PMID 25653011, 2015). "Taken together, these data suggest that miR-503 may function as a previously unknown tumor suppressor in ER+ breast cancer, and that a critical component of its tumor suppressor role could be the repression of DDHD2 via a non-canonical mechanism." (PMID 25653011, 2015). "However, of this group of genes, only FGFR1 and DDHD2 were shown to function as oncogenes in breast cancer, and DDHD2 was shown to have transforming potential that was not dependent on FGFR1 expression." (PMID 25653011, 2015).
Cognitive impairment (5 papers, 2015 to 2025). Abnormal cognition is characterized by deficits in thinking, reasoning, or remembering. "A better understanding of the DDHD2-regulated lipid pathways may offer critical insights into the mechanisms of synaptic plasticity and therapeutic strategies for cognitive disorders." (PMID 38316990, 2024).
schizophrenia (4 papers, 2020 to 2024). A major psychotic disorder characterized by abnormalities in the perception or expression of reality. "For instance, DDHD2 was found for schizophrenia, which is a new candidate risk gene recently discovered based on its effects on RNA-binding protein dysregulation." (PMID 34807913, 2021).
atherosclerosis (3 papers, 2013 to 2024). A disease characterized by the build-up of fatty material and calcium deposition in the arterial wall resulting in partial or complete occlusion of the arterial lumen. "In conclusion, our findings suggest that radiation-induced endothelial ferroptosis accelerates atherosclerosis, and DDHD2 is a potential regulatory protein in radiation-induced endothelial ferroptosis through the Nrf2/GPX4 pathway." (PMID 39062593, 2024).
breast tumors (2 papers, 2015 to 2016). "DDHD2 is located in a region of the genome that is frequently amplified in breast tumors, and most frequently in ER+ breast tumors." (PMID 25653011, 2015). "In addition, DDHD2 was observed to be located in a region (8p11.23) of high level copy number aberrations in breast tumors." (PMID 25653011, 2015). "In breast tumours the 8p11-12 amplicon is broad resulting in increased copy number of FGFR1 and of multiple neighboring genes and studies have shown that some of these neighboring genes, for example WHSC1L1, BAG4 and DDHD2, can be oncogenic." (PMID 26905262, 2016).
memory impairment (2 papers, 2024 to 2025). "In humans, biallelic mutations of DDHD2 cause HSP54, a disorder characterized by progressive memory impairment and motor neuron dysfunction." (PMID 41028912, 2025). "In contrast, DDHD2 knockout mice exhibited a significant reduction in the response of saturated FFAs (especially myristic acid) even prior to the onset of memory impairment." (PMID 38316990, 2024). "To further investigate cognitive effects of DDHD2 knockout, we adopted a longitudinal novel object location (NOL) test to investigate short-term spatial memory impairment." (PMID 38316990, 2024).
neuroblastoma (2 papers, 2023). Neuroblastoma (NB) is the most common solid, extracranial childhood tumor. "In this study, we further investigated the enzymatic properties and functions of DDHD2 in neuroblastoma cells and primary neurons." (PMID 37832604, 2023). "We found that DDHD2 hydrolyzes multiple acylglycerols in vitro and substantially contributes to neutral lipid hydrolase activities of neuroblastoma cells and brain tissue." (PMID 37832604, 2023). "Using neuroblastoma cells and primary neurons as model systems, we found that DDHD2 engages in the lipolysome as dual DAG/TAG lipase and cooperates with ATGL in neuronal lipolysis." (PMID 37832604, 2023). "Consistently, elevated sn-1,3 DAG levels were a primary consequence of DDHD2 inhibition in neuroblastoma cells." (PMID 37832604, 2023). "Substrate promiscuity of DDHD2 allowed its engagement at different steps of the lipolytic cascade: In neuroblastoma cells, DDHD2 functioned exclusively downstream of ATGL in the hydrolysis of sn-1,3-diacylglycerol (DAG) isomers but was dispensable for TAG hydrolysis and lipid droplet homeostasis." (PMID 37832604, 2023). "To understand how DDHD2 interacts with other cytosolic lipases in the regulation of cellular TAG metabolism, we inhibited lipase activity in Neuro-2a neuroblastoma cells using small molecule inhibitors and shRNA-mediated gene silencing." (PMID 37832604, 2023).
papillary thyroid cancer (2 papers, 2021 to 2022). "In papillary thyroid cancer (PTC), circRUNX1 promotes PTC progression and metastasis by sponging miR-296-3p and regulating DDHD domain containing 2 (DDHD2) expression." (PMID 36522683, 2022).
spastic ataxia (2 papers, 2014 to 2022). "Herein, we describe Japanese siblings exhibiting a midlife-onset spastic ataxia with a novel homozygous DDHD2 mutation found by exome-sequencing." (PMID 25417924, 2014).
breast invasive carcinoma (1 paper, 2015). "Analysis of DDHD2 alterations using the cBio portal revealed that DDHD2 tends to be amplified in a variety of cancers, and most predominantly in breast invasive carcinoma (~12% of cases)." (PMID 25653011, 2015).
Chanarin‐Dorfman syndrome (1 paper, 2020). "Patients with other disorders that lead to TG accumulation, that is, defects in DDHD2 and Chanarin‐Dorfman syndrome, have similar lipid resonances in brain MR spectra." (PMID 32557630, 2020).
dementia (1 paper, 2024). Loss of intellectual abilities interfering with an individual's social and occupational functions. "Consequently, DDHD2 may be an important pharmacological target to alter saturated FFAs in the context of memory in ageing and dementia." (PMID 38316990, 2024).
GM1 gangliosidosis (1 paper, 2016). A rare lysosomal storage disorder characterized biochemically by deficient beta-galactosidase activity and clinically by a wide range of variable neurovisceral, ophthalmological and dysmorphic features. "We obtained a genetic diagnosis in 4/9 (44 %) families within known HSP genes (DDHD2 and CYP2U1), as well as perixosomal biogenesis disorders (PEX16) and GM1 gangliosidosis (GLB1)." (PMID 27679996, 2016).
hereditary spastic paraplegia 54 (1 paper, 2025). "Biallelic mutations in DDHD2 can disrupt its membrane-binding domain and abolish phospholipase and triglyceride hydrolase activities, causing hereditary spastic paraplegia 54 (HSP54), a childhood-onset autosomal recessive disorder marked by progressive neuromuscular and cognitive impairments." (PMID 41028912, 2025).
cancer (11 papers, 2015 to 2025). A tumor composed of atypical neoplastic, often pleomorphic cells that invade other tissues. "An upregulated level of CircRUNX1 was observed in cancer samples to control the miR-296-3p/DDHD2 axis associated with metastasis formation and tumour growth." (PMID 39558949, 2024). "DDHD2 has been reported to act as an oncogene in various cancers, but its role in PTC remains unknown." (PMID 33479208, 2021).
tumor (8 papers, 2010 to 2025). "The strong antitumor effect of miR-296-3p and the tumor-promoting effect of DDHD2 were further investigated in PTC, indicating that circRUNX1 modulates PTC progression through the miR-296-3p/DDHD2 pathway." (PMID 33479208, 2021). "The aneuploidic increases in copy number of genes that may promote tumor formation, including ARHGAP26, GRB10, DDHD2, FGFR1, CTNNA3, PTPN1 and MLLT1 in the apparently stable and karyotypically normal lines HS293 and HS401, are cause for concern." (PMID 20428235, 2010). "In summary, we demonstrated that miR-503 represses cell proliferation, and may function as a tumor suppressor in ER+ cancer by utilizing non-canonical 3′ pairing to target and repress the proto-oncogene DDHD2." (PMID 25653011, 2015). "In addition, we showed that miR-503 acts like a tumor suppressor by non-canonically targeting the putative oncogene DDHD2." (PMID 25653011, 2015).
neurological disorders (3 papers, 2018 to 2025). "Given that DDHD2 mutations are associated with complex neurological disorders, it will be critical to investigate whether impaired myristoylation contributes to synaptic dysfunction in these conditions." (PMID 40528004, 2025).
cardiovascular disease (1 paper, 2022). "Six genes (TKT, TCF4, SWAP70, DDHD2, ARHGAP31, and LTB) showed significant associations of genetic variants with the risk of cardiovascular disease." (PMID 36204511, 2022).
DDHD2 also shares sentences with these, for which no sentence is quoted: Obesity (8 papers); hepatic steatosis (5); Insulin resistance (5); hypertriglyceridemia (4); hepatoma (3); infection (3); liver steatosis (3); acne (2); acute pancreatitis (2); hyperlipidaemia (2); pancreatitis (2); Parkinson disease (2); Strabismus (2); Alzheimer disease (1); amyotrophic lateral sclerosis (1); Ataxia (1); ataxia telangiectasia (1); autism (1); bladder cancer (1); brain disorder (1); Cachexia (1); cervical cancer (1); cognitive disorder (1); complex hereditary spastic paraplegia (1); developmental delay (1); Dyslipidemia (1); episodic ataxia (1); gastric cancer (1); genetic disorder (1); Hyperglycemia (1).
A further 21 diseases each share a sentence with DDHD2 in 1 paper.